NLRP3 (NLR family pyrin domain containing 3)
Diseases named in the same sentence as NLRP3 in open-access papers (continued):
Sharing a sentence is not in itself a finding about the gene and the disease.
tumor (continued). "However, studies in chemically induced colitis model showed that the mice lacking NLRP3 are highly susceptible to tumor formation with severe inflammation." (PMID 27429614, 2016). "While it is clear that NLRP3 might interfere with cancer cell growth by modulating the inflammatory state of the tumor microenvironment, it cannot be excluded that NLRP3 itself has a direct role, acting on intracellular pathways responsible for the modulation of cell growth or apoptosis." (PMID 27221966, 2016). "The close functional association between P2X7R and NLRP3 and the known, albeit controversial, role of IL-1β in tumor progression, initially prompted us to hypothesize that NLRP3 followed in CLL lymphocytes an expression pattern similar to P2X7R, and thus was overexpressed." (PMID 27221966, 2016). "Moreover, NLRP3 inflammasome plays a significant role in tumor control by recruiting neutrophils, which may provide a prognostic marker and promising therapeutic target in cancer patients." (PMID 27652274, 2016). "How NLRP3 recruits MDSCs into the tumor environment is unknown." (PMID 24273542, 2013). "Thus, it could be hypothesized that dysfunctional mitochondria in cancer cells activate the NLRP3 inflammasome, leading to an increase in tumor-promoting pro-inflammatory cytokines." (PMID 24273542, 2013). "This study identifies NLRP1 and NLRP3 inflammasomes as potential biomarkers and therapeutic targets in NMSC, linking their altered expression to tumour progression and recurrence." (PMID 42222687, 2026). "Tissue immunofluorescence (IF) was applied to investigate the colocalization expression of NLRP3 and ASC in tumor cells." (PMID 41847892, 2026). "StromalScore analysis suggested that NLRP3 and AIM2 were activated by the tumor immune microenvironment in KIRC." (PMID 41808837, 2026). "Dying tumor cells treated with chemotherapy release ATP, which activates the NLRP3 inflammasome and IL-1β–IL-1 receptor (IL-1R) signaling in dendritic cells, driving an effective CD8 T-cell response against transplantable tumor cells." (PMID 40718836, 2025). "In this study, we aimed to determine both the potential mechanistic synergy between STING and NLRP3 agonists, and the effects of this innate immune combination on the GBM tumor immune landscape." (PMID 40377974, 2025). "Compared with RTMs in the normal tissue, a subset of mo-Macs in the tumor overexpressed TET3 and NLRP3, consistent with mouse scRNA-Seq studies." (PMID 40794443, 2025). "A previous study indicated that AKK, through the TLR2/NLRP3 signaling pathway, can induce the production of a significant amount of iNOS in M1-type TAM, thereby inhibiting tumor development." (PMID 41170411, 2025). "The NLRP3 inflammasome represents a critical cellular pathway intricately involved in CRC pathogenesis, with significant implications for tumor progression and therapeutic targeting." (PMID 40869140, 2025). "In accordance with the NLRP3 expression variation, the GFAP + PTX scaffold promoted a significant increase in the caspase-1 expression in tumor cells compared with the GF + PTX scaffold (p < 0.05), strengthening the results obtained previously." (PMID 39940603, 2025). "NLRP3 inhibitors, such as MCC950, have demonstrated potential in reducing inflammation and enhancing anti-tumor immunity by repressing immune checkpoint expression and promoting apoptosis in cancer cells." (PMID 39966334, 2025). "It has been established that the NLRP3 inflammasome can modulate the TME by regulating inflammatory status and immune cell phenotypes, thereby influencing tumor behavior." (PMID 40718836, 2025). "P.g. and F.n. upregulate IL-1β mRNA/protein via AIM2 and NLRP3 inflammasome dysregulation in an OSCC cell line, promoting a pro-tumor inflammatory phenotype." (PMID 40924302, 2025). "Here, we discuss the implications of NLRP3, AIM2 and NLRC4 inflammasomes in both cancer development and tumor suppression as well as the potential for future investigations in this context." (PMID 40692785, 2025).
tumor (continued). "Both parental viruses (rVSV and rNDV) have been shown to induce the formation of the NLRP3 inflammasome, leading to gasdermin (GSDM)-controlled pyroptotic death and a pro-inflammatory anti-tumor immune response." (PMID 40896365, 2025). "The low-risk group had significantly higher infiltration of immune cells, which primarily have anti-tumor immune functions, and showed a higher sensitivity to ICIs therapy, possibly acting through the AL365361.1/hsa-miR-17-5p/NLRP3 axis." (PMID 40352941, 2025). "This inference was based on previous evidence linking NLRP3 inflammasome activation and ALKBH7-mediated mitochondrial stress to immune modulation within the tumor microenvironment." (PMID 41373809, 2025). "Compared to the control group, the absolute numbers of CD45+CD8+ cells in the tumor, normalized by tumor weight, were significantly higher in the chemo > STING/α-PD-1 + α-CTLA-4 and chemo > NLRP3/α-PD-1 + α-CTLA-4 groups, with an increase exceeding 10-fold." (PMID 39871312, 2025). "Further supporting a role in tumor progression, P.g. and F.n. inhibit CHK1 activation while upregulating NLRP3 gene expression in OSCC cells, promoting growth." (PMID 40924302, 2025). "The results showed elevated levels of AIM2 in tumor tissues, while CASP1, NLRP3, and NLRP1 exhibited low expression in these tumor tissues." (PMID 40026444, 2025). "The pyroptosis‐related markers NLRP3, HMGB1, and caspase‐1 are known to regulate inflammatory signaling and modulate the tumor microenvironment." (PMID 41479846, 2025). "It is possible that chemotherapy-induced tumor cell death released the tumor antigens, which synergized with STING and NLRP3 agonist-induced innate immune responses." (PMID 39871312, 2025). "We then evaluated the diagnostic performance of multiple markers, including salivary and fecal microbiota, routine blood tests, blood lipids, serum tumor markers, and the NOD-like receptor protein 3 (NLRP3) inflammasome, both individually and in combination." (PMID 40520898, 2025). "In mouse models of NSCLC, cucurbitacin B effectively inhibits tumor growth and shows superior anti-tumor effects compared to standard treatments, underscoring its potential as a targeted therapy through the TLR4/NLRP3/GSDMD signaling axis." (PMID 40149884, 2025). "Pyroptosis is regulated by key molecules, including NOD‐like receptor family pyrin domain containing 3 (NLRP3), high mobility group box 1 (HMGB1), and caspase‐1, which are involved in inflammatory signaling and tumor microenvironment modulation." (PMID 41479846, 2025). "One study examined tissue samples from 43 CRC patients and demonstrated that the activation of the NLRP3 inflammasome correlated with EMT induction and tumour grade." (PMID 41148809, 2025). "ATP released from dying cancer cells activate P2X7 receptors on DCs leading to activation of the NLRP3 inflammasome, IL-1β release and priming of IFN-γ-producing tumor antigen-specific CD8+ T cells." (PMID 39995666, 2025). "Utilizing the NLRP3 inhibitor, MCC950, on lung cancer cells, has been shown to delay the tumorigenic process and immobilize anti-tumor responses in cancer patients." (PMID 41376623, 2025). "Cancer cells can influence key molecules in the NLRP3 pathway, resulting in TAM reprogramming toward a pro-inflammatory state that supports tumor progression." (PMID 40141358, 2025). "In the GSE53819 dataset, we identified 914 genes positively correlated with NLRP3 expression and 1272 genes downregulated in NPC tumor tissues compared to normal tissues." (PMID 39951856, 2025). "In this context, several data reported the dual role of the inflammasome in BC, in that a pro- and anti-tumor activity of the NLRP3 and AIM2 inflammasomes was, respectively, suggested in this type of tumor." (PMID 40002808, 2025). "Next, we examined the effects of STING or NLRP3 agonists and their based combinations on the antigen presenting process in the orthotopically implanted KPC tumor model." (PMID 39871312, 2025).
tumor (continued). "Since there are reports of NLRP3 and IL-1 involvement in MDSC expansion and suppressor function in tumor models, we next assessed the role of the NLRP3/IL-1 axis on AC-induced MDSC expansion and suppressor function." (PMID 40530419, 2025). "The tumor markers, inflammatory factor, mRNA and protein expression of TLR4/NF-κB/NLRP3 inflammasome related indicators in serum and esophageal tissue was determined by ELISA, qPCR, and western blot (WB) respectively." (PMID 40606986, 2025). "Persistent exposure to polystyrene NPs has been shown to activate signaling cascades such as ROS/NLRP3 and MAPK, resulting in the release of pro-inflammatory cytokines and chemokines that create a permissive niche for tumor cell proliferation and invasion." (PMID 41003403, 2025). "For instance, EZH2’s dual role in suppressing tumor suppressor genes (e.g., CDKN1A, NLRP3) while activating pro-survival signals (e.g., Snail/EGFR) highlights its adaptability as a molecular switch in resistance trajectories." (PMID 40701777, 2025). "NLRP3 does so by enhancing IL-1β level, which, in turn, mediates the EMT and develops a pro-inflammatory environment that promotes tumor progression." (PMID 39941895, 2025). "These compounds enhance ROS generation and activate pathways comprising signaling molecules like NLRP3, MEK/ERK1/2, and JNK, thereby promoting tumor cell death while fostering an immune-stimulatory tumor microenvironment." (PMID 40149884, 2025). "Certainly, P. gingivalis and F. nucleatum promoted the proliferation and progression of OSCC cells in vitro by overexpressing NLRP3 and activating the ATR-CHK1 molecules, promoting tumour growth." (PMID 41440367, 2025). "For instance, IL-6 has been shown to activate NLRP3 via the JAK2/STAT3/SOX4 axis, effectively connecting inflammatory cytokine signaling with inflammasome-mediated tumor enhancement." (PMID 41560727, 2025). "Subsequent cluster analysis based on mRNA expression indicated effective differentiation between tumor and normal tissues along the PC1 axis depending on their respective GLI1 and NLRP3 levels." (PMID 39744485, 2025). "PTX treatment significantly increased inflammasome activation, as indicated by significantly increased NLRP3, ASC, NOD2 and AIM2 (p < 0.0001) expression in MDA-MB-231 tumor cells compared to control cells." (PMID 39433537, 2024). "Another NLRP3 inhibitor, gli, was shown to suppress the formation of inflammasome assembly by inhibiting the P2X7 receptor, expressed in many cells within the tumor microenvironment." (PMID 38543085, 2024). "Along with the increase of NLRP3, ASC and IL-1β expression levels, an increasing caspase-1 expression profile was obtained for PTX-treated tumor cells compared untreated cells." (PMID 39433537, 2024). "Therefore, NLRP3 has been speculated to be a novel target for tumor therapy." (PMID 39144184, 2024). "This demonstrated complete tumor regression in 80% of LLC tumor-bearing mice, works by activating the NLRP3 pathway." (PMID 39318624, 2024). "In this context, the aim of the current study was to obtain an effective PTX-based anti-tumor strategy targeting NLRP3 inflammasome using both pharmaceutical modulation assisted by ATP and MCC950 and gene silencing protocol using NLRP3 specific siRNA." (PMID 39433537, 2024). "The protein expression level of NLRP3, caspase 1, GSDMD, IL-1β and IL-18 in XRZYBXD high dose group were also significantly higher than those in the tumor model group by WB." (PMID 40046008, 2024). "However, the mechanism by which NLRP3 inflammasome regulate tumor progression is currently unknown." (PMID 38317229, 2024).
tumor (continued). "Such analysis demonstrated an increase in NLRP3 and IL1B gene expression in tumor-infiltrating myeloid cells, which was consistent with transcriptomic results from in vitro experiments." (PMID 38576612, 2024). "The mRNA relative expression level of NLRP3, Caspase 1, GSDMD, IL-1β and IL-18 in XRZYBXD high dose group were significantly higher than those in the tumor model group by Q-PCR." (PMID 40046008, 2024). "Studies indicate that directing interventions towards ZBP1, caspases, NLRP3, RIPK1, and RIPK3 can trigger a robust anti-tumor immune response, facilitating the efficient eradication of cancer cells." (PMID 38553639, 2024). "The main mechanisms by which mtDNA induces ICD in tumor immunotherapy involve the cGAS-STING signaling pathway, toll-like receptor 9, and NLRP3 inflammasome." (PMID 39916954, 2024). "First of all, the administration of PTX facilitated NLRP3 complex assembly and pyroptosis activation in MDA-MB-231 tumor cells." (PMID 39433537, 2024). "Cisplatin activates the MEG3/NLRP3/caspase-1/GSDMD pathway to induce pyroptosis in triple-negative breast cancer (TNBC), thereby inhibiting tumor growth and metastasis." (PMID 38654314, 2024). "Early studies have shown that activation of NLRP3 induces adaptive immunity to tumors, and that IL-1β released during this process is required for the priming of IFN-γ-producing, tumor-antigen-specific CD8+ T cells." (PMID 38553639, 2024). "However, colchicine could impair testosterone synthesis, attenuating the effect the testosterone on the NLRP3 inflammasome-related tumor genesis activity, leading to colchicine may play a positive role for protecting the cancer formation (negative effect on the aHR)." (PMID 38649928, 2024). "The activation of NLRP3 inflammasome in human DLBCL cell lines and its correlation with PD-L1 expression highlights its role in the shaping of a tumor-promoting immune tumor microenvironment." (PMID 38397043, 2024). "A nanoparticle-mediated cytotoxic drug can selectively be delivered to cancer cells via exotoxin A to activate NLRP3, cleave GSDMD, and mediate pyroptosis at the primary tumor site." (PMID 39062587, 2024). "Deletion or overexpression of NR1D1 in the tumor microenvironment increased or reduced lung tumor development in an NLRP3 inflammasome-dependent manner, suggesting that NR1D1 acts as a tumor suppressor in the lung tumor microenvironment." (PMID 37524704, 2023). "Significantly higher expression of NLRP3 and (NT-)GSDMD were observed in knockdown-LINC00969 derived tumours treated with gefitinib." (PMID 37156816, 2023). "Cucurbitacin B (CuB), a compound extracted from muskmelon pedicel, inhibits tumor growth in NSCLC cells by directly binding to TLR4, activating the NLRP3 inflammasome and inducing pyroptosis." (PMID 37752941, 2023). "GSDMD (p = 0.012) and IL-18 (p < 0.001) were highly expressed in tumor tissues, whereas NLRP3 (p < 0.001) and CASP1 (p = 0.001) expression was low in tumor tissues." (PMID 37864196, 2023). "On the other hand, NLRP3 in DCs and AIM2 in macrophages have been shown to facilitate anti-tumor immunity." (PMID 36932407, 2023). "LPS/ATP increased the size of the tumor spheres in MDA-MB-231 cells, which had a high NLRP3 expression and IL-1β release." (PMID 36902278, 2023). "Indirectly, mitoxantrone induces anti-tumor immunity against fibrosarcoma, characterized mainly by enhanced CD8+ T cell activation, through myeloid cell-derived IL-1β produced by NLRP3 inflammasomes." (PMID 36932407, 2023).
tumor (continued). "Additional research has shown that arctiin is able to suppress inflammation, fibrosis, and the migration of tumor cells by inhibiting STAT3, TGF-β1, TLR4, NLRP3, VEGF, and cyclin D1." (PMID 37701157, 2023). "Blockade of FATP2 inhibited NLRP3 activation in MDSCs, IL-17 production in CD4+ T cells, and the tumour recurrence post fatty liver IRI." (PMID 37916155, 2023). "The results showed that treating a human granulosa-like tumor cell line (KGN) with metformin significantly decreased LPS-induced expression of miR-670-3p, NOX2, NLRP3, ASC, cleaved caspase-1, and GSDMD-N." (PMID 37244286, 2023). "In addition, our results suggest that HDM predominantly activates the NLRP3 inflammasome in macrophages, but we cannot exclude that other cell types such as neutrophils and/or eosinophils also contribute to IL-1β secretion and to the tumor-promoting effect of HDM." (PMID 36670473, 2023). "We found that tumor implantation into macrophagic NLRP3-depleted mice significantly reduced CD163-CD68+ M1 macrophages and significantly increased CD163+CD68+ M2 macrophages compared to tumor implantation into control mice." (PMID 37077909, 2023). "During fatty liver graft injury, arachidonic acid activated NLRP3 inflammasome in MDSCs through FATP2, which subsequently stimulated CD4+ T cells producing IL-17 to promote tumour recurrence post transplantation." (PMID 37916155, 2023). "IHC staining utilizing both NLRP3 antibody and HIF-1A antibody further confirmed the tumor cells with elevated HIF-1A showed enhanced inflammasome in its microenvironment." (PMID 36720864, 2023). "Subsequently, we conducted clustering and LASSO analysis on each tumor and found that the inhibitory and the stimulating immune checkpoints positively correlate with ZBP1, NLRP3, CASP1, CASP8, and TNFAIP3." (PMID 38002938, 2023). "Another mechanism contributing to the development of adaptive resistance to anti-PD-1 immunotherapy is the activation of the tumor-intrinsic NOD-, LRR- and pyrin domain-containing protein-3 (NLRP3) inflammasome–heat shock protein 70 (HSP70) signaling axis." (PMID 37849764, 2023). "This highlights the impact of NLRP3 inflammasome activity on the interaction between PDAC cells and macrophages and their tumor microenvironment." (PMID 38018872, 2023). "The tumor-promoting effect of HDM was significantly decreased by heat treatment of the HDM extract and was inhibited by NLRP3, IL-1β, and CCL2 neutralization, or ICS treatment." (PMID 36670473, 2023). "Genetic deletion and pharmacologic inhibition of NLRP3 enabled the development of Th1 immunity, increased intratumoral levels of IL2, CD8+ T cell–mediated tumor suppression, and ultimately limited tumor growth." (PMID 37772994, 2023). "By inhibiting NLRP3-dependent IL-18, RAI16 maintained intestinal homeostasis and inhibited tumor development." (PMID 37833958, 2023). "Further investigation demonstrated that arctiin suppresses inflammation, fibrosis, and tumor cell migration by inhibiting STAT3, TGF-β1, TLR4, NLRP3, VEGF, and cyclin D1." (PMID 37701157, 2023). "We found that arachidonic acid activated NLRP3 inflammasome in MDSCs through FATP2 during fatty liver graft injury, which led to more IL-17 secretion of CD4+ T cells and promoted tumour recurrence post transplantation." (PMID 37916155, 2023). "This study also reported that systemic NLRP3 inhibition suppressed PMN-MDSC recruitment and, along with PD-1 therapy, inhibited tumor progression more effectively than PD-1 monotherapy." (PMID 37242422, 2023). "In this study, a significant reduction in NLRP3, ASC, IL-1β, and IL-18 expression was shown in the tumor’s samples from BAY-117082-treated mice compared to the OSCC group." (PMID 37345134, 2023). "Most measured immune pathways were upregulated in the XRT + NLRP3 ± α-PD1 groups, as compared to control or XRT alone, and this was true for both tumor models tested." (PMID 37289257, 2023).